GPC3 (glypican 3)
Diseases named in the same sentence as GPC3 in open-access papers (continued):
Sharing a sentence is not in itself a finding about the gene and the disease.
tumor (continued). "In fact, these are well known indicators for poor prognosis and early tumor recurrence in patients with HCC, for instance, glypican 3, MicroRNA-29, hyaluronic acid, Ski-interacting protein, interleukin-6, VEGFR2, IL-17 and IL-17RE, G2890 N-glycan, GGT and miR-24-3p." (PMID 25970775, 2015). "Immunohistochemical analysis of tumor cells indicated the following: HMB-45(+); vimentin(+); smooth muscle actin (SMA)(+); melan-A(+); CK(−); hepatocyte(−); Arg-1(−); GPC-3(−); CK7(−); CK19(−); CK20(−); S-100(−); CD34 blood vessel endothelium(+); and no exact tumor suppository." (PMID 26698563, 2015). "A previous functional analysis revealed that GPC3 promotes HCC cell migration and invasion, which may lead to tumor progression." (PMID 25625609, 2015). "GPC3 may inhibit IGF and Wnt signaling, which are critical for cell motility and tumor progression, indicating that GPC3 may act as a metastasis suppressor." (PMID 25140302, 2014). "High GPC3 expression tended to be correlated with the presence of tumor size ≥ 5 cm in three studies, thought it was not significant difference." (PMID 24548704, 2014). "In an IFN-γ ELISPOT assay, the HLA-A*02:01-restricted GPC3144–152 peptide-specific CTLs produced IFN-γ in the presence of GPC3-expressing tumor cells, HepG2 and SK-Hep-1/GPC3, without peptide pulse." (PMID 23143746, 2013). "The tumor cells were CK8, CK18, CD30, glypican 3, and PLAP positive." (PMID 24294529, 2013). "In contrast, GPC3144–152 peptide-specific CTLs did not produce IFN-γ against GPC3-negative tumor cells, SW620 and SK-Hep-1/vec, without peptide pulse." (PMID 23143746, 2013). "Interestingly, a significant positive correlation between GPC3 expression and CD45−CD90+ cancer stem cells was found in the HCC tumor tissues (Spearman r = 0.5997, P<0.0001)." (PMID 22606345, 2012). "Besides, GPC3 has been shown to induce ERK1/2 and AKT phosphorylation that eventually contributes to anti-apoptosis, invasion, and survival of tumor cells." (PMID 22606345, 2012). "Immunohistochemistry revealed strong GPC3 expression in 34 out of forty-two HCC tumor tissues (80.9%), but no expression was detected in non-tumorous tissues." (PMID 22606345, 2012). "Immunohistochemically, the tumor cells were positive for GPC3, AFP, hepatocyte antigen, HepPar1, and CK18, but negative for CK7, CK20, PLAP, PSA, CA125, EMA, CD117, and CEA." (PMID 21443783, 2011). "In addition, GPC-3 expression stimulates the recruitment of macrophages into HCC, especially macrophages with a phenotype promoting tumour progression and metastasis." (PMID 20465843, 2010). "The marker glypican-3 was strongly positive (30-100%) for all tumours and no HepPar-1 staining was found." (PMID 20167095, 2010). "Non-neoplastic tissue adjacent to the tumor included myometrium (n = 5), endometrium (n = 6), cervix (n = 2) and alveolar lung tissue (n = 3) all of which were negative for GPC3 with no background staining seen." (PMID 20868507, 2010). "In this study, all the canine tumours with a K19 expression had 30-100% positivity for glypican-3; all the other hepatocellular tumours were negative for glypican-3." (PMID 20167095, 2010). "Among patients from cohort B, GPC-3 levels exhibited a weak correlation with the size of the major HCC nodule (rs = 0.201, 95% CI 0.085–0.312; p = 0.001), and were significantly higher in patients with multifocal HCC than those with unifocal tumor (123, 69–226 pg/mL vs. 74, 43–149 pg/mL; p < 0.001)." (PMID 41511652, 2026). "We find that Trem2 deficiency synergizes with GPC3-CAR-T to enhance tumor control by expanding endogenous tumor-specific CD8+ T cells (not CAR-T amplification) and reeducating TAMs to an anti-tumor CXCL9hi/SPP1lo phenotype via metabolic reprogramming." (PMID 41564864, 2026). "It is speculated that the expression of GPC3 may be activated in the early stages of tumorigenesis and maintained at a relatively stable level without significant changes during tumor progression." (PMID 41471145, 2025).
tumor (continued). "From a clinical perspective, a bispecific tracer could prove most valuable in lesions with heterogeneous marker expression—where GPC3 is low in some niches but PSMA remains high in neovasculature, or vice versa—thus maximizing detection sensitivity across diverse tumor phenotypes." (PMID 40722645, 2025). "Notably, GPC3-targeted CAR-T therapies have demonstrated promising anti-tumor activity in xenograft models and early-phase trials, although challenges related to toxicity and the tumor microenvironment remain." (PMID 40722645, 2025). "Importantly, anti–glypican-3 CAR Vδ1 cells with secreted IL-15 co-expression augmented in vivo anti-tumor activity compared to those without secreted IL-15 co-expression." (PMID 40148988, 2025). "Moreover, in previous studies using subcutaneous models, anti‐GPC3 CAR‐T cells controlled small tumour growth but failed to inhibit tumours with a higher burden." (PMID 41267637, 2025). "A second oncogenic signal, such as c-Met or glypican-3, is required for the Wnt/β-catenin pathway to contribute to HCC development; targeting these oncogenic signal molecules in combination with inhibition of the Wnt/β-catenin signaling promotes tumor regression." (PMID 41142820, 2025). "The comparative evaluation of PSMA and GPC3—each with distinct biological rationales—will be critical in defining the optimal biomarker for HCC theranostics, particularly as we move toward personalized paradigms that integrate imaging phenotypes with molecular and histologic tumor characteristics." (PMID 40722645, 2025). "More recently, GPC3-CAR-T cells were engineered to co-express IL-21 and CXCL9, which, alongside blockade of the checkpoint inhibitor PD-1, were shown to offer a combo of increased cytokine secretion, proliferation, chemotaxis, and overall ameliorated anti-tumor activity." (PMID 41465318, 2025). "Tumour epithelial cells were further reclustered into two distinct subclusters (Subcluster 1 and Subcluster 2), and DUSP9 was predominantly expressed in Subcluster 1, which was enriched with other oncofetal and stemness‐related genes such as AFP, GPC3, IGF2, ANPEP and EPCAM." (PMID 41383134, 2025). "For CAR-T approaches targeting GPC3, early-phase studies report on-target toxicity risks, including cytokine release syndrome (CRS) and potential on-target, off-tumor effects if low-level GPC3 is expressed in normal tissues; close monitoring and step-up dosing strategies may mitigate these risks." (PMID 40722645, 2025). "bsAbs that target oncofetal protein GPC3 and 4-1BB are already in preclinical development (PRS-342) and might be promising candidates in directing and stimulating recently activated 4-1BB+ TILs to HCC tumour tissues." (PMID 38440738, 2024). "Among the non-immune cells, apart from a small population of tumor-associated endothelial cells (21 cells, 0.07% of the total cells, marked with VWF and ENG), the rest were cancer cells (11,228 cells, 35.46% of the total cells, marked with GPC3 and ASS1)." (PMID 38169544, 2024). "Given their efficacy in terms of tumor cytotoxicity in xenograft tumor models, future clinical evaluations of allogeneic CAR/sIL-15 Vδ1 T cells in the treatment of GPC-3-expressing tumors, including HCC, is highly expected, since it might offer a safe and effective off-the-self product." (PMID 38338658, 2024). "designed GPC3 CAR-T cells co-expressing IL-15 and IL-21 and observed robust expansion and sustained persistence of these T cells in their HCC xenograft models; the resulting tumor control and survival rates were higher than those with CAR-T cells equipped with only one cytokine or the other." (PMID 39430751, 2024). "Also, tumor markers (AFP, GPC3, and VEGF) were significantly enhanced in the HCC group." (PMID 37759583, 2023). "Also, PD-1-deleted GPC3-CART cells show enhanced in vivo anti-tumor activity against HCC without impairing GPC3-CART cell activation and proliferation." (PMID 37569693, 2023).
tumor (continued). "However, the proposed model is advantageous because GPC3 expression in HCC tumor tissue is directly assessed by MRI exams without the need for peripheral blood and radiation caused by CT scans." (PMID 38023195, 2023). "It was found that GPC3 was highly expressed in the tumor tissues compared with the non-HCC tissues according to The Cancer Genome Atlas (TCGA) cohort (n = 369), the RNA-seq (n = 65) and MS data (n = 152) of Mengchao Hepatobiliary Hospital of Fujian Medical University." (PMID 37665421, 2023). "In addition, investigators described T cells were redirected to GPC3+ tumor cells by GPC3‐ENG MSCs, which may become a GPC3‐targeted treatment method." (PMID 34981659, 2022). "Due to the very high positive rate of Ki-67, Hep-par1, GPC-3, Ki-67, and GS (> 95%), we could not find any correlation with viral DNA or surface antigen within tumor." (PMID 35034659, 2022). "In addition, TJ12P1 was able to detect GPC3 protein in HCC patient-derived tumor tissue but not in healthy adult-derived liver tissue." (PMID 36077433, 2022). "No staining was observed in the SK-HEP-1 xenograft tumor (no GPC3 expression)." (PMID 35853994, 2022). "Univariable and multivariable logistic regression analysis firstly identified tumor c (odds ratio [OR], 0.361; 95% CI: 0.158, 0.826; P = 0.02) and serum AFP levels over 20 ng/mL (OR, 8.117; 95% CI: 2.422, 27.199; P = 0.001) as two independent predictors of GPC3-positive HCCs." (PMID 36518314, 2022). "While it may be too early to confer the role of transcription factor to FAT1 for upregulation of EMT and stemness genes, it would now be fascinating to study the impact of GPC3 (and other GPC isoforms) interaction on FAT1 signaling event that initiates at the cell membrane of tumor cells." (PMID 33878524, 2021). "However, GPC3 shows elevated expression in HCC and contributes to tumor progression." (PMID 33878524, 2021). "Furthermore, expression of p62 (100%) and glypican-3 (70%) were found to be upregulated in HCC tumor samples, whereas no p62 and glypican-3 were detected in matching controls, indicating impaired autophagic flux in these sets of HCCs samples." (PMID 33976943, 2021). "More importantly, the F3 peptide labeled with radioactive 68Ga could successfully detect GPC-3-positive HCC tumors in vivo and the PET imaging analysis revealed a high uptake of tumor compared to the minor background accumulation (4.50 ± 1.20 to 0.27 ± 0.14% ID/g)." (PMID 34150644, 2021). "The tumor cells did not express HepPar-1, glypican-3, S-100, CK7, and CK19 in the liver tumor." (PMID 32590784, 2020). "We examined 100 GPC3-positive cells from each tumor in the whole bone marrow-transplanted mice and found that these cancer cells did not contain Y chromosomes, indicating that these tumor cells were originated from the female donor bone marrow." (PMID 32296582, 2020). "Following GPC3-synNotch-GFP and CD147-CAR-mCherry cotransduction of T cells and primed by the CD147koGPC3high-HepG2, the cytotoxic activities of transduced T cells were triggered by different subsets of HCC cell lines for 2 h to assess specific tumor-killing efficacy." (PMID 32968061, 2020). "Dual-targeting CAR-T cells coexpressing GPC3 and asialoglycoprotein receptor 1 (ASGR1, a liver tissue-specific protein) targeting CAR’s featuring CD3 zeta chain (CD3ζ) and 28BB (containing both CD28 and 4-1BB signaling domains) have been tested in a GPC3+ASGR1+ HCC tumor xenograft mouse model." (PMID 32968061, 2020). "Differential expression of GPC3 in non-tumor versus tumor samples varies by organ." (PMID 31956905, 2020). "As in AFP and GPC3 detection, ATAD2 may become a prospective molecular biomarker, allowing for the early diagnosis and treatment of HCC patients, thereby avoiding the adverse effects of tumor progression." (PMID 32462022, 2020). "The tumor cells did not express HepPar-1, glypican-3, S-100, CK7, and CK19 (data not shown)." (PMID 32590784, 2020).
tumor (continued). "In this study, LSPMbs were labelled with Cy5.5 for targeting GPC3 imaging evaluation, the results showed that they had not presented aggregated fluorescence imaging, indicating that LSPMbs were not targeting retained in the tumor." (PMID 33354418, 2020). "But there is some leakiness in response to GPC3-negative tumor cell SK-Hep-1." (PMID 31921693, 2019). "Moreover, we found that GPC3 can also inhibit PGC-1α-mediated mitochondrial oxidative phosphorylation, which provides new evidence for mitochondrial respiration inhibition not necessarily just as a consequence of increased glycolysis in tumor cells." (PMID 31781603, 2019). "As expected, these transduced NK92 cells selectively activated and secreted IL12 in response to the GPC3-positive tumor cells, while only very limited expression could be observed in the presence of GPC3-negative SK-Hep-1 cells." (PMID 31921693, 2019). "Thus far, in our study, we have not further elucidated the inverse expression of GPC3 in tumor tissue and corresponding serum exosomes in GEA." (PMID 31100935, 2019). "The expression status of MCT4 and GPC3 was not evaluated in whole tumor sections." (PMID 31706332, 2019). "Tumor cells were positive for Hep Par-1 and glypican-3, and negative for cytokeratin (CK) 7, CK20, thyroid transcription factor 1 (TTF-1), inhibin, OCT3/4, prostate-specific antigen (PSA), prostatic specific acid phosphatase (PSAP), renal carcinoma marker (RCC), and PAX8." (PMID 30268151, 2018). "In fact, Py-GPC3 could suppress the tumor growth but could not eradicate tumor cells, which might be due to small portion of GPC3-expressing tumor cells in subcutaneous HCC tissues." (PMID 28445973, 2017). "Tumor differentiation and microvascular invasion were shown to have significant associations with the expression of NKCC1 (p<0.05), keratin 19 and Ki-67 but not glypican-3." (PMID 29029515, 2017). "The non-tumor regions of all HCCs stained negative for GPC3 and IGF-1R." (PMID 29113314, 2017). "However, the tumor cells were completely negative for hepatocyte antigen, Glypican-3, CK20, and CDX-2." (PMID 27301956, 2016). "Moreover, HS20 also showed an inhibitory effect on HepG2 tumor growth; after GPC3 was knocked down, tumor growth was no longer inhibited." (PMID 26332121, 2015). "All tumours were negative for glypican-3 and strongly positive for HepPar-1." (PMID 20167095, 2010). "Additionally, GPC3-targeted antibody-drug conjugates (ADCs), such as codrituzumab (GC33) (e.g., NCT01507168), have shown specific tumor localization and acceptable toxicity profiles in clinical studies, though their efficacy may be further enhanced by combinatorial approaches." (PMID 41154412, 2025). "Therefore, immunotherapy using a specific antibody against a GPC3 antibody may be ineffective for HCC treatment because of the lack of a tumor-specific CTL response." (PMID 36139670, 2022). "We found significantly decreased levels of Afp (a marker of undifferentiated HCC), Spp1, Gpc3 (markers of early HCC), and Epcam (a marker of stemness), suggesting that Myc-R26Met tumours might be more differentiated and at more advanced stages than Alb-R26Met tumours." (PMID 36433941, 2022). "GPC3 CAR-T cells were injected via the tail vein into tumor-bearing mice treated with or without AAV-CCL19 for 7 days to further verify whether the better antitumor effect produced by the combination of CAR-T cells and AAV was due to the chemotactic effect of CCL19 on T cells." (PMID 34527749, 2021). "In addition, alternative pathways not involved in physiologic GPC3 function, such as the Yap-Hippo pathway as has been shown in adult liver tumors, may also contribute to GPC3-mediated pediatric tumor development." (PMID 30873384, 2019). "GPC3 expression on used HCC cell lines in our study was analyzed by flow cytometry and we also detected the HLA and NKG2D ligand expression on the HCC cell line Huh-7 in order to prove that GPC3-Syn-NK92 cells may not be activated by these tumor characteristics." (PMID 31921693, 2019).
tumor (continued). "As the PrimeCAR-T method significantly improved the anti-tumor effects compared with conventional CAR-T in mouse models, clinical trials of the PrimeCAR-T therapy for solid cancers are anticipated and its application to the GPC3-targeted therapy may be a very promising approach." (PMID 31510063, 2019). "Thus, the on-target, off-tumor toxicity of the GPC3-CAR T cell might occur, even if without the disruption of the PD-1." (PMID 30327605, 2018). "When combined with LNP-engineered GPC3-specific CAR-NK cells, this approach elicited synergistic antitumor activity, as demonstrated by superior tumor lysis in vitro and robust tumor regression in various HCC models without systemic toxicity." (PMID 41803088, 2026). "In GPC3-negative SNU449 tumors, T1-weighted MRI showed no appreciable difference in tumor signal intensity or CNR between the ET58-DOTA-Gd and DOTA-Gd groups." (PMID 41154412, 2025). "GPC3 is derived from the cell surface and expression is elevated in the tissues and serum of HCC patients but is low or absent in adjacent non-tumor lesions and benign liver diseases, suggesting its potential as a diagnostic marker for HCC." (PMID 41471145, 2025). "To assess the in vivo tumor-targeting performance of 1G12-DOTA-Gd, we performed T1-weighted MRI in subcutaneous xenograft mouse models of GPC3-negative SNU449 cells or GPC3-positive HepG2 cells, using DOTA-Gd as the control." (PMID 41154412, 2025). "In the GPC3-negative SNU449 model, no notable difference in tumor signal enhancement was observed between DOTA-Gd and 1G12-DOTA-Gd; the CNR over time was also comparable between DOTA-Gd and 1G12-DOTA-Gd." (PMID 41154412, 2025). "Immunohistochemical staining of the tumor in the present case showed that the tumor tissue was negative for AFP, Glypican-3, and CK19, thus ruling out the diagnosis of HCC." (PMID 40978045, 2025). "Immunohistochemical staining showed that the tumor tissue was positive for CgA, Syn, S - 100, CD10, and CD34, but negative for AFP, cytokeratin 19 (CK19), CK7, GS, GPC3, HSP70, with a Ki-67 labeling index of 2%." (PMID 40978045, 2025). "Immunohistochemical staining plays a crucial role in diagnosing PGL, as it typically demonstrates that tumor cells are positive for CgA, Syn, NSE, and CD56 while negative for epithelial markers such as CK, EMA, and GPC3." (PMID 40978045, 2025). "The tumor cells stained positive for CD56, CD99, and S-100, and negative expression of Glypican-3, NSE, SYN, and CGA was observed using immunohistochemical analysis." (PMID 36805679, 2023). "In summary, we developed a strategy to modify NK cells with Gpc3 aptamers (G-NK cells), which can specifically target GPC3+ HCC tumor cells to significantly enhance NK cell cytotoxicity without genetic modification in vitro and in vivo." (PMID 37665421, 2023). "The neoplasm was positive for CK7, CK19, and synaptophysin; weakly positive for pCEA and chromogranin; and negative for nuclear β-catenin, Hep-Par1, glypican-3, alpha-fetoprotein, and glutamine synthetase." (PMID 36782322, 2023). "GPC3 CAR NK‐92 cells effectively reduced the tumor burden in xenografts, importantly, the degree of tumor growth inhibition was not affected by the expression level of GPC3 in HCC cells." (PMID 38045827, 2023). "GPC3 is an ideal target for TRAB because its expression in normal tissues is very low16, unlike other TRAB tumour antigens." (PMID 36071036, 2022). "Among all patients, nine (75%) did not develop tumor recurrence up to 24 weeks and displayed stronger IFN-γ-producing CTL responses against AFP, MAGE-1, and/or GPC-3 antigens than the others who developed recurrence after vaccination." (PMID 36139542, 2022). "Here the authors show that a combination of chemotherapy and ERY974, a bispecific antibody that targets glypican-3 and CD3, facilitates T cell infiltration and promotes anti-tumor responses also in non-inflamed tumors." (PMID 36071036, 2022).